MTOR (mechanistic target of rapamycin kinase)
Diseases named in the same sentence as MTOR in open-access papers (continued):
Sharing a sentence is not in itself a finding about the gene and the disease.
cancer (continued). "Previous research has shown that CSCs regulate the occurrence and development of cancer through the PI3K/AKT/mTOR, Wnt/β-catenin, Notch, and Hedgehog pathways." (PMID 39703688, 2024). "Everolimus, an mTOR inhibitor, has been widely used in combination cancer therapies and has successfully enhanced the efficacy of platinum-based treatments." (PMID 39857585, 2024). "The interactions between PD-1 and PD-L1 of cancer cells inhibit T cell activation by blocking the signaling of T cell receptors through the activation of the mTOR and MAPK pathways, thereby inhibiting Drp1 activation." (PMID 38340166, 2024). "Dysregulation of protein synthesis is a common characteristic of MYC-driven cancers and is marked by increased Pol I-mediated ribosomal rDNA transcription and mTOR/eIF4E-driven mRNA translation." (PMID 39574899, 2024). "Overall, these findings suggest that MAC increases the anti-cancer activity of 5-FU by suppressing the phosphorylation of Akt/mTOR/p70S6K, as well as nuclear β-catenin expression in CRC cells." (PMID 38891932, 2024). "Metformin has also been found to inhibit the mammalian target of the rapamycin (mTOR) signaling pathway, which regulates cell growth, proliferation, and survival in some cancers, thus stopping tumor growth and progression." (PMID 39202556, 2024). "BCAAs are essential for cancer cell growth via the activation of the mTOR pathway to promote protein synthesis and serving building blocks for proteins and substrates for energy production." (PMID 39795113, 2024). "Both THBS1 and THBS2 share the TSR2 domain that interacts with the epidermal growth factor receptor (EGFR), which in turn is known to activate the PI3K/Akt/mTOR downstream signal pathway, known to be involved in cancer cell growth and survival." (PMID 38339060, 2024). "This has led to the development of numerous mTOR inhibitors with varying mechanisms of action, some of which are currently undergoing clinical trials for different types of human cancers." (PMID 38891085, 2024). "In prostate cancer patients, Exendin-4 has been observed to enhance the response to chemotherapy and reduce cancer growth by activating the PI3K/Akt/mTOR pathways." (PMID 39333445, 2024). "Second, drugs targeting mTOR partners which crosstalk with mTOR signaling pathway in diverse cancers have been used combined with mTOR inhibitors." (PMID 39349424, 2024). "Sorafenib activates apoptotic cells in human cancer by reducing the levels of the p-Akt, p-mTOR, and p-ERK pathways." (PMID 38527038, 2024). "The targeted inhibition of mTOR has been recently demonstrated to be a mechanistic basis for cell hibernation in ESCs and cancer cells." (PMID 38418814, 2024). "The PI3K/mTOR signaling pathway, modulating tumor initiation and development in many types of cancers, is a potential candidate to predict the response to radiochemotherapy." (PMID 38741069, 2024). "In the context of cancer, mTOR ensures the unlimited cell division, which is essential for cancer growth." (PMID 38960924, 2024). "Knockdown of caveolin-1, a principal structural component of caveolar membrane domains derived from lipid rafts, suppresses cancer development via the inhibition of PI3K/Akt/mTOR signaling, motility, and metastasis of breast carcinoma MDA-MB-231 cells." (PMID 39329960, 2024). "Cyclic adenosine 3′,5′‐monophosphate (cAMP) level in cancer cells also affects the Akt/mTOR pathway." (PMID 39723045, 2024). "Glutamine is a critical amino acid for cancer cell growth and proliferation based on its connection to mTOR activation, nucleotide and protein synthesis, ATP production, lipid synthesis, and antioxidant machinery." (PMID 38891084, 2024).
cancer (continued). "We also identified somatic changes in cancer-associated pathways, such as PI3K/Akt/mTOR, cell cycle, and NOTCH signaling pathways, and structural chromosomal defects such as chromosome doubling." (PMID 39158654, 2024). "Cancer cells often upregulate the expression of key glycolytic enzymes, such as GLUT1, HK2, and MCT1, which are implicated in the mammalian target of rapamycin (mTOR) signaling pathway." (PMID 39479443, 2024). "mTOR inhibitors are therapeutically promising for targeted therapy of cancer and other mTOR-related diseases." (PMID 38824577, 2024). "To investigate the mechanistic processes behind TDO’s involvement in VEGF-induced proliferation of HUVECs, we studied the activation of mTOR, a pathway known to be related to angiogenesis in many cancers." (PMID 38794128, 2024). "Treatment strategies for PTC include the use of immunosuppressants with fewer side effects, Treg cell therapy, infection screening and vaccination, mTOR inhibitors for cancer treatment, and CAR‐T cell therapy and Treg depletion therapy." (PMID 39224537, 2024). "Studies have shown that DAU can inhibit the PI3K/AKT/mTOR signaling pathway, inducing autophagic apoptosis in cancer cells by mediating ROS generation." (PMID 39215261, 2024). "The occurrence of several changes in cancer is mostly due to heightened activation of the PI3-K/Akt/mTOR pathway." (PMID 39204369, 2024). "Aberrant activation of the EGFR/MAPK/mTOR/AKT/ERK1/2 signaling pathway occurs in a variety of human cancer cells." (PMID 38762741, 2024). "As the PI3K/Akt/mTOR pathway plays a crucial role in cancer growth, its inhibition by specific targeted inhibitors has been shown to lead to regression in human tumors in the preclinical setting." (PMID 38539472, 2024). "CCL5, a ligand of CCR5, is a product of cancer itself and its microenvironment, using the mTOR pathway through the regulation of cyclin D1, c-Myc, and Dad-1 expression to enhance tumor growth." (PMID 39329983, 2024). "Cholesterol and its derivatives are not only precursors of many sterols with potentially signaling properties, but also activate mTOR directly in cancer cells." (PMID 38267699, 2024). "The increase in autophagy signaling is a potential contributor to the effects of mTOR inhibition on cancer prevention." (PMID 38976168, 2024). "Metformin activates AMPK, a key regulator of cellular energy metabolism, and inhibits the AKT/mTOR pathway, resulting in reduced cancer cell growth and proliferation." (PMID 39333445, 2024). "mTOR is a serine–threonine kinase and a key intracellular point of convergence for several pathways in human cancer and thus represents an important therapeutic target." (PMID 38400671, 2024). "According to recent studies pharmacological treatments that inhibit mTOR signaling and ribosome synthesis have the potential to slow the progression of cancer." (PMID 39162964, 2024). "The activity of mTOR complexes is recommended to be assessed and considered in cancers before mTOR inhibitor therapy, as current first-generation mTOR inhibitors (rapamycin and analogs) can be ineffective in the presence of mTORC2 hyperactivity." (PMID 38515456, 2024). "The insulin/insulin-like growth factor (IGF) signalling pathway to mTOR is essential for the survival and growth of normal cells and also contributes to the formation and progression of cancer." (PMID 39558974, 2024). "Calycosin activates the SIRT1/AMPK axis to inhibit the Akt/mTOR pathway, stimulating autophagy-mediated apoptosis in cancer cells." (PMID 39403142, 2024). "Our findings provide novel possibilities for treating cancers using pDNA-tachyplesin and stimulating the mTOR and NFκB signaling pathways." (PMID 38691208, 2024). "The regulation of ASCT2 and LAT1/2 expression is controlled by AMPK and mTOR, which are fundamental for energetic metabolism in cancer." (PMID 38392995, 2024).
cancer (continued). "mTOR is at the intersection of multiple signaling frameworks that govern the physical phenotype of cancer cells and transduce extracellular mechanical cues." (PMID 38201302, 2024). "Further, the effects of TAN on the modulation of inflammation-mediated cancer-related pathways including PI3K/AKT/mTOR, Notch, and MAPK signaling, suppressing cell proliferation and inducing autophagy in various types of cancer cells, has also been addressed." (PMID 38672774, 2024). "The activation of mTOR signaling drives the variations seen in cancer cell metabolism, including pathways for amino acid, glucose, nucleotide, fatty acid, and lipid metabolism." (PMID 38474373, 2024). "Compound 18 was found to be capable of inhibiting PI3K/mTOR kinases, which oversee controlling a variety of cellular functions in human cancer cells." (PMID 38686058, 2024). "Ultimately, Akt activates the mammalian target of rapamycin mTOR (specifically the mTORC1 complex), regulating the downstream effectors, which are deeply involved in cancer cell proliferation, survival, angiogenesis and drug resistance." (PMID 39199632, 2024). "The suppression of BCAA catabolic enzyme expression leads to an accumulation of BCAA and to the hyperactivation of the mTOR pathway in cancers." (PMID 39795113, 2024). "Key genes such as COL1A1, COL4A1, PIK3CA, PIK3R1, and mTOR were found to be overexpressed, correlating with increased cancer aggressiveness." (PMID 39850811, 2024). "These direct effects are linked to liver kinase B1 (LKB1)-mediated activation of AMP-activated protein kinase (AMPK) and suppression of mammalian target of rapamycin (mTOR) signaling and protein synthesis in cancer cells." (PMID 38611893, 2024). "The mTOR signaling pathway is exploited by approximately 30% of cancers, contributing to their development and progression due to its various roles that impact the cell cycle, growth, survival, and metabolism." (PMID 38892329, 2024). "The PI3K/Akt/mTOR signaling pathway promotes cell growth, invasion, and angiogenesis and prevents cell apoptosis in various cancers." (PMID 39273340, 2024). "These enzymes are integrated into key signaling pathways such as NF‐κB and PI3K/Akt/mTOR, essential for regulating cellular processes critical to cancer development." (PMID 39678489, 2024). "The PI3K/AKT/mTOR pathway plays a crucial role in regulating cell survival, growth, proliferation, and metabolism, with its disruption being common in cancer and other diseases." (PMID 39239068, 2024). "Recent evidence has prompted a reevaluation of the role of the mTOR pathway in cancer development leading to new conclusions." (PMID 38418814, 2024). "Several studies emphasize the significance of the PI3K/Akt/mTOR pathway in cancer, with its dysregulation in almost all human cancers, including breast cancer, colorectal cancer, and hematologic malignancies." (PMID 38296798, 2024). "As one of the most frequently modified signaling pathways, thePI3K-Akt-mTOR axis activation maintained cancer growth." (PMID 38626574, 2024). "Activated PI3K/Akt/mTOR signaling drives angiogenesis, cancer cell metabolism, growth, and survival, highlighting the potential of therapies that show activity in the CNS and target this oncogenic signaling axis for the treatment of DIPG." (PMID 38319732, 2024). "mTOR inhibitor treatment in non-cancer cell lines increases polyomavirus LT-antigen expression and directly activates polyomavirus replication by inhibiting S-phase kinase-associated protein 2 (Skp2) E3 ligase at non-cytotoxic concentrations." (PMID 38940554, 2024). "This indicates that Parishin A effectively inhibits the activation of the PI3K/AKT/mTOR pathway, thereby disrupting the signaling mechanisms essential for cancer cell maintenance." (PMID 39458918, 2024). "Metformin also exerts its influence on cancer cells by modulating the AMPK/mTOR pathway and inhibiting cytokines." (PMID 38612893, 2024).
cancer (continued). "Aberrant activation of the PI3K/AKT/mTOR pathway is involved in several cellular processes in cancers, including metastasis, EMT, autophagy, apoptosis and chemoresistance." (PMID 38178023, 2024). "Irregularities in the major components of the PI3K/AKT/mTOR signaling pathway are common in human cancers." (PMID 38213733, 2024). "Metformin inhibits cancer cell growth by blocking the LKB1/AMPK/mTOR/S6K1 pathway, leading to selective cell death in GSCs and inhibiting the proliferation of CD133+ cells." (PMID 38891882, 2024). "Unsurprisingly, mTOR signaling is frequently hyperactivated in cancer, which contributes to the nutrient metabolism reprogramming of cancer cells." (PMID 39048994, 2024). "The PI3K/AKT/mTOR pathway tends to be overactivated by cancer, which is considered a promising therapeutic target." (PMID 38755125, 2024). "Research indicates that dysregulated activation of the AKT/mTOR pathway in EC tissues can enhance cancer proliferation, invasion, and metastasis, while suppressing apoptosis and accelerating tumor malignancy." (PMID 39759103, 2024). "First-generation mTOR kinase inhibitors, everolimus, temsirolimus, and rapamycin, have found wide application in clinical cancer therapies, but drug resistance limits their efficacy." (PMID 39596342, 2024). "Activation of the PI3K/AKT/mTOR pathway, driven by PIK3CA mutations, can confer a survival advantage to cancer cells, promoting uncontrolled proliferation and resistance to apoptosis." (PMID 39369580, 2024). "In cancer cells, constitutive activation of the mTOR pathway promotes several hallmarks of cancer, including increased protein synthesis, lipid metabolism, and inhibition of autophagy, which are vital for rapid cell growth and proliferation." (PMID 39564119, 2024). "The GSEA results for SIGLEC9 suggest that it is involved in processes regulated by MYC, mTOR, and E2F, pathways commonly engaged in the control of cancer cell growth and survival." (PMID 39727942, 2024). "To investigate the impact of Akt-mTOR inactivation on IMT1-induced anti-cancer activity, we introduced the lentivirus carrying a constitutively-active S473D mutant Akt1 (caAkt1) into pCan-1 cells." (PMID 39227564, 2024). "KEGG pathway enrichment analysis indicates that DEAATGs are primarily linked to protein digestion and absorption, ferroptosis, central carbon metabolism in cancer, and the mTOR signaling pathway." (PMID 39698464, 2024). "Another recent study reported that FTO-induced upregulation of flotillin-2 contributed to cancer aggressivness in diffuse large B-cell lymphoma by activating PI3K/Akt/mTOR pathway." (PMID 39744011, 2024). "The mTOR pathway is commonly activated in human cancers and plays a crucial role in tumor progression, emphasizing the need for further investigation into the molecular mechanism of abnormal metabolism in HCC." (PMID 39000273, 2024). "By binding to p55, Tspan9 suppresses the activation of PI3K/Akt/mTOR signaling and promotes cell autophagy in gastric cancer, thereby inhibiting the resistance of cancer cells to 5-fluorouracil." (PMID 38389703, 2024). "Previous studies in cancer cell lines have demonstrated that mTOR also acts as a lipid sensor and phosphatidic acid (PA), a key intermediate of de novo phospholipid and triglyceride biosynthesis, is the form of lipid that modulates mTOR activity." (PMID 38223199, 2024). "The mTOR signaling pathway is frequently activated in ESCC, providing a theoretical basis for targeting mTOR in cancer treatment 9,10." (PMID 38725843, 2024). "The mTOR inhibitor sirolimus was approved in 1999 for immunosuppression in kidney transplantation, yet its application in cancer still poses significant challenges." (PMID 38791529, 2024). "Consistent with the oncogenic role of TP63 in SCC, genes positively correlated with TP63 expression were enriched in cancer-promoting hallmark pathways, including E2F targets, G2M checkpoint, MYC targets and mTOR signaling pathways." (PMID 38509096, 2024).
cancer (continued). "The hyperactivation of the MTOR pathway is increasingly recognized as a driver of tumor recurrence and drug resistance across multiple cancer types, including ESCC." (PMID 39742278, 2024). "The mTOR pathway is a crucial regulatory pathway found in various cancer types, affecting proliferation and survival." (PMID 39600313, 2024). "AKT‐independent mechanisms downstream of PI3K and mTOR can also be involved in cancer cell survival and apoptosis." (PMID 39092562, 2024). "Advances in DNA sequencing and analysis of human cancer genomes have revealed that the PI3K-Akt-mTOR pathway is commonly dysregulated in cancers arising from diverse tissues of origin." (PMID 38616230, 2024). "The Akt/mTOR pathway can be activated during the development of a variety of human cancers and is considered a relevant therapeutic target." (PMID 38668684, 2024). "Dysregulation of mTOR signaling fosters cancer development through a myriad of events, including the involvement of Mammalian Enhancer-of-Akt-1-7 (mEAK-7), which activates alternative mTOR signaling." (PMID 39796034, 2024). "Given its centrality to survival and proliferation, the PI3K/AKT/mTOR pathway is a target for cancer therapies." (PMID 39770406, 2024). "Network pharmacology predicted the EGFR/PI3K/Akt/mTOR pathway as a potential key pathway for the anti-cancer effect of black ginseng." (PMID 39200424, 2024). "It is worth noting that Phospholipase D (PLD), a lipid-metabolizing enzyme, also regulates the PI3K/AKT/mTOR signaling pathway in cancer cells." (PMID 39594764, 2024). "The inhibition of the Akt/mTOR-dependent signaling pathway reduces anabolic pathways, decreases glucose uptake, and produces less lactate in a variety of cancer cell lines via down-regulating PKM2 expression." (PMID 39273552, 2024). "FADD overexpression was associated with the activation of several cancer-related pathways, such as the MAPK and MTOR signaling pathways." (PMID 38684755, 2024). "The effect of apigenin on CRC occurs by inhibiting the PI3K/Akt/mTOR pathway, which is considered an important therapeutic target due to its abnormal activation in many cancers (Sain, Kandasamy, and Naskar 2022)." (PMID 39723045, 2024). "The mammalian target of rapamycin (mTOR) signaling pathway is involved in the manner in which cancer cells sense physical changes." (PMID 38201302, 2024). "The PI3K/AKT/mTOR signaling pathway plays an important role in the progression of various cancers and plays an extremely important role in cell growth, survival, proliferation, angiogenesis, autophagy, and other processes." (PMID 38482051, 2024). "As mentioned, HNC has alterations in the PI3K/AKT/mTOR signalling pathway, highlighting its universal role in cancer progression." (PMID 39518152, 2024). "S6K2 is a downstream effector of mTOR, with a well-established role in cancer, albeit to a lesser extent than S6K1." (PMID 39796034, 2024). "Elevated mTOR activity is commonly observed in various types of cancer and is also increased in the ischaemic and fibrotic environment of non-functional kidneys in ESRD patients." (PMID 38341510, 2024). "Ivermectin has been reported to achieve its anti-cancer effect through multiple diverse paths, including the inhibition of multidrug resistance proteins, the Akt/mTOR pathway, and other tumor progression pathways." (PMID 38794139, 2024). "AKT/mTOR signaling pathway is hyperactive in cancer cells, facilitating cancer cell growth and proliferation." (PMID 39328201, 2024). "The studies have confirmed that luteolin can inhibit cancer-cell survival and proliferation, angiogenesis, invasion, metastasis, mTOR/PI3K/Akt, STAT3, Wnt/β-catenin, and cell-cycle arrest, and induce apoptosis." (PMID 38474604, 2024). "Evidence that mTOR suppression leads to a dormant state in tumor cells followed by translational reprogramming should be taken into account under cancer treatment with dual mTORC1/2 inhibitors to prevent possible fatal consequences in patients." (PMID 38418814, 2024).